TNF (tumor necrosis factor)
Diseases named in the same sentence as TNF in open-access papers (continued):
Sharing a sentence is not in itself a finding about the gene and the disease.
Insulin resistance (continued). "Several inflammatory cytokines including TNF-a, IL-1b, and IL-6 have been identified as being involved in the development of insulin resistance." (PMID 27525022, 2016). "Both TNF-α and NF-κB play important roles in insulin resistance and β-cell dysfunction and contribute to the pathogenesis of T2D, and lipid disorders." (PMID 26877773, 2016). "Tumor necrosis factor-α (TNF-α) is overproduced in the adipose tissue of obese animals and humans and contributes to the insulin resistance by targeting several components of the insulin signaling pathway." (PMID 28042862, 2016). "IRS-1 is an important factor in the insulin signaling pathway, and TNF-α diminishes insulin-induced tyrosine phosphorylation of IRS-1 during the process of insulin resistance." (PMID 27324794, 2016). "HFD also increases plasma levels of TNF-α, a cytokine that contributes to insulin resistance and vascular dysfunction." (PMID 27562094, 2016). "TNF-α is believed to induce insulin resistance by a number of mechanisms such as increase in serine phosphorylation of IRS-1, which disrupts the insulin signaling cascade." (PMID 27379252, 2016). "With the associations between inflammatory cytokines (e.g., IL-6, TNF-α, and hs-CRP) and insulin resistance, prediabetes or T2DM had been widely researched." (PMID 27478850, 2016). "Regarding the connection between inflammation and insulin resistance, it is known that TNF-α induces insulin resistance in vitro and in mice." (PMID 26788518, 2016). "TNF-α is a potent cytokine with many adverse effects such as insulin resistance and activation of lipolysis." (PMID 27023799, 2016). "TNF-α induces vascular insulin resistance by mechanisms that involve positive modulation of PTEN and inhibition of Akt/eNOS/NO signaling." (PMID 27562094, 2016). "TNF-α was the first proinflammatory cytokine detected in adipose tissue and is involved in the regulation of insulin resistance." (PMID 27247565, 2016). "For example, IL-10 has been shown to prevent diet-induced insulin resistance, and IL-6 and TNF are known to decrease levels of the protective adipokine adiponectin." (PMID 27148273, 2016). "As a well-known factor involved in insulin resistance, tumor necrosis factor-α (TNF-α) also impairs GLP-1 secretion from the intestinal L-cells." (PMID 26728801, 2016). "On the other hand, it is well known that LPS induces pro-inflammatory cytokines, such as tumor necrosis factor (TNF)-α, which play a critical role in insulin resistance and hepatic inflammatory cell recruitment in NAFLD." (PMID 27304953, 2016). "High IL-10 levels, for example, have been reported to promote insulin sensitivity in humans and protect against insulin resistance by diminishing TNF mediated intracellular signaling in adipocytes." (PMID 27239103, 2016). "One study indicated that the activation of p42/p44 and p38 MAPK by TNFα impaired insulin stimulation of IRS-2 associated PI3K, leading to insulin resistance in brown adipocytes." (PMID 26903879, 2016). "In continuation of our work on TNFα-induced retinal insulin resistance, we measured SOCS3 and IRTyr960 in the BBZDR/Wor lean and obese rats alone and treated with salicylate." (PMID 25874611, 2015). "Among these cytokines, tumor necrosis factor-α (TNF-α) was the first cytokine identified to be capable of inducing insulin resistance in adipocytes in vitro." (PMID 26779183, 2015). "To study this, we used the TNFα model of insulin resistance in 3T3-L1 adipocytes, which has been reported to be reversed by treatment with the PPARγ agonist pioglitazone." (PMID 26240143, 2015). "In this work, cell lysis-free multicolor cellular imaging-based mechanism study for TNF-α-induced insulin resistance is introduced." (PMID 25623542, 2015). "More than 20 years ago, it was shown that the pro-inflammatory cytokine TNF-α was capable of inducing insulin resistance." (PMID 26300887, 2015).
Insulin resistance (continued). "Experimental models of insulin resistance demonstrated amelioration of inflammation, increased insulin sensitivity, and improved steatosis upon treatment with infliximab, a potent TNFα neutralizing monoclonal antibody." (PMID 26090470, 2015). "TNFα, through NF-κB both promotes and is activated by insulin resistance and is involved in liver inflammatory and metabolic alterations." (PMID 26090470, 2015). "Amygdalin and cinnamic acid were examined to elucidate their molecular mechanism on the suppression of TNF-α-induced insulin resistance using multicolor cellular imaging based on QDot nanoprobe." (PMID 25623542, 2015). "Both high concentrations of TNF-α and free fatty acids produced by obese adipose tissue play a crucial role in the pathogenesis of insulin resistance." (PMID 26308010, 2015). "Although increased TNFα expression in adipose tissue has been shown to promote to insulin resistance in overweight and obese rodent models, there was no indication that the HFD increased renal tissue expression of this inflammatory cytokine." (PMID 26185688, 2015). "TNF-α, a proinflammatory cytokine that is activated by the reactive oxygen species created by lipid peroxidation, not only promotes insulin resistance, but also mediates cholesterol and triglyceride metabolism." (PMID 26221176, 2015). "Elevated levels of PIMT in skeletal muscle of HSD fed rats and TNF-α treated myoblasts suggested a potential role for PIMT in the skeletal muscle insulin resistance." (PMID 26468734, 2015). "miR-15b and miR-16 play a role in the inhibition of insulin resistance via reduced TNFα and SOCS3 signaling and increased IGFBP-3 levels, resulting in REC protection from hyperglycemia-induced apoptosis." (PMID 25888955, 2015). "In obese subjects, macrophages infiltrate into livers and adipose tissue and secrete pro-inflammatory cytokines (including IL-6 and TNF-α) and lead to insulin resistance." (PMID 26519255, 2015). "Similar to TNF-alpha, IL-6 is a proinflammatory adipokine that correlates with body weight and insulin resistance." (PMID 26640706, 2015). "Adipocyte dysfunction and its associated adipocyte cell hypertrophy and production of pro-inflammatory cytokines, such as interleukin 6 (IL-6) and tumor necrosis factor alpha (TNF-α), also contribute to the development of insulin resistance and T2D." (PMID 26407933, 2015). "Consistent with previous studies, peroxisome proliferator-activated receptor (PPAR) γ agonism reversed TNFα-induced insulin resistance." (PMID 26240143, 2015). "In view of its beneficial activities, melatonin has successfully been used in rats with MetS diminishing insulin resistance, release of TNF-α and IL-6 from adipocytes, low-density lipoprotein, and very low-density lipoprotein plasma levels and body weight." (PMID 25759691, 2015). "Macrophages, lymphocytes, and trophoblast cells are the main producers of the proinflammatory cytokine TNFα, which also contributes to insulin resistance." (PMID 26346343, 2015). "This prompted the studies to establish the linkage between an inflammatory phenotype characterized by increased levels of TNF-α and other pro-inflammatory cytokines and insulin resistance." (PMID 26336514, 2015). "In the current study, we examined the role of PP4 in TNF-α-induced hepatic insulin resistance both in vivo and in vitro." (PMID 26666849, 2015). "In response to eHSP70, macrophages can release IL-1β, IL-6, and TNFα, all cytokines involved in insulin resistance." (PMID 25814786, 2015). "Taken together, we show that PIMT/phospho PIMT facilitates TNF-α induced insulin resistance in skeletal muscle." (PMID 26468734, 2015). "We found that increased expression and activity of PP4 occurred in the livers of db/db mice and TNF-α-induced hepatic insulin resistance both in vitro and in vivo." (PMID 26666849, 2015). "The developed assay successfully verified that cinnamic acid and amygdalin suppressed TNF-α-induced insulin resistance mainly via the inhibition of JNK." (PMID 25623542, 2015).
Insulin resistance (continued). "In the current study, we identified that the transcriptional co-activator binding protein, PIMT, is an important mediator of TNF-α induced skeletal muscle insulin resistance." (PMID 26468734, 2015). "In obese mice, adipose-derived TNF-α is involved in insulin resistance through the activation of JNK, leading to increased inhibitory serine phosphorylation of insulin receptor substrate-1 (IRS-1pSer) in muscle." (PMID 25617315, 2015). "TNF-α promotes insulin resistance by inhibiting the IRS1 (insulin receptor substrate 1) signaling pathway." (PMID 26307961, 2015). "TNF-alpha is over-expressed in the adipose tissue of obese subjects in proportion to the degree of insulin resistance." (PMID 25634659, 2015). "Insulin resistance in adipocytes induced by TNFα is accompanied by an increased GM3 biosynthesis through the up-regulation of GM3 synthase (ST3GAL5) gene expression." (PMID 25955839, 2015). "TNF-α is a signature proinflammatory cytokine that promotes the expression of other inflammatory cyto-/chemokines and induces insulin resistance by inhibiting IRS-1 signaling pathway." (PMID 26200663, 2015). "These animals presented augmented ALT, triglycerides, IL-1β and TNF-α levels and insulin resistance and the histological alterations of NASH such as collagen deposition, macro/microvesicular steatosis, and liver fibrosis." (PMID 26064924, 2015). "Pregnancy is characterized by an increase in insulin resistance due to the increase of cortisol, progesterone, human placental lactogen, and tumor necrosis factor α and the decrease of adiponectin." (PMID 26010910, 2015). "Increased levels of plasma glucose, insulin, malondialdehyde, tumor necrosis factor-alpha, and insulin resistance and decreased levels of glutathione, glutathione peroxidase, and catalase were found in rats on a high fructose diet." (PMID 25650289, 2015). "In the present study, we identified PP4 as a novel regulator in hepatic insulin resistance induced by TNF-α." (PMID 26666849, 2015). "TNFα knock-out animal models are resistant to the development of insulin resistance in animal strains prone to diet-induced obesity (DIO mice) or those that lack leptin (Ob/Ob mice)." (PMID 26415887, 2015). "Blood samples were obtained for estimation of total cholesterol and triglycerides, insulin, glucose, insulin resistance, tumor necrosis factor alpha (TNF-α), interleukin 12 (IL12), and interleukin 10 (IL-10)." (PMID 25944984, 2015). "Taken together, these results demonstrate that miR-15b and miR-16 play a role in the inhibition of insulin resistance via reduced TNFα and SOCS3 signaling and increased IGFBP-3 levels, resulting in REC protection from hyperglycemia-induced apoptosis." (PMID 25888955, 2015). "This study demonstrated that OA attenuated insulin resistance in HepG2 cells, whose effect is possibly mediated through decreasing the levels of TNF-α and IL-6 and regulating the expression of IRS1 and GLUT4 protein via the NF-κB protein." (PMID 26843885, 2015). "TNFα plays a crucial role in insulin resistance through the down-regulation of insulin-stimulated glucose uptake, insulin receptor auto-phosphorylation and insulin receptor substrate-1." (PMID 25685071, 2015). "Activation of TLR-4 results in NF-κB activation and subsequent induction of vascular pro-inflammatory cytokines e.g. TNF-α and IL-1β that have also been demonstrated in inflammation after sub-acute and chronic stress and insulin resistance." (PMID 25826421, 2015). "In the present work, we have shown that oleate did not induce insulin resistance in the context of cardiovascular cells and moreover it is capable of protecting against insulin resistance induced by palmitate or TNF-α." (PMID 26055507, 2015). "M1 macrophages accumulated in adipose tissue produce various inflammatory mediators such as IL-6 and TNF-α and promote the development of insulin resistance." (PMID 25816341, 2015).
Insulin resistance (continued). "The increased expression of TNFα and IL-1β likely contribute to the insulin resistance observed in the KI mice, as increased expression of these cytokines in skeletal muscle are associated with higher insulin resistance." (PMID 26405763, 2015). "Adipokines, such as tumor necrosis factor-α (TNF-α), interleukin-1β (IL-1β), and interleukin-6 are associated with development of insulin resistance and vascular disease." (PMID 25826421, 2015). "TNFα is a major driver of insulin resistance in skeletal muscle and, in addition, it can also induce activation of stress signals in pancreatic β-cells, leading to mitochondrial dysfunction that culminates in cell failure and death." (PMID 25814786, 2015). "It has been more than two decades since the link between inflammation and insulin resistance was first shown with an increase in TNFα levels in obese rodents." (PMID 26217222, 2015). "Second, this myocardial insulin resistance was mediated partly by increased TNF-α production from the ischemic heart." (PMID 26659007, 2015). "Taken together, these results demonstrate that local cardiac overexpression of TNF-α mimics myocardial insulin resistance, and exacerbates poor heart function observed with surgically-induced MI." (PMID 26659007, 2015). "We also checked that parthenolide, an inhibitor of NF-κB, prevented IκB-α degradation and therefore the activation and translocation of NF-κB to the nucleus in addition to prevent insulin resistance induced by TNF-α or palmitate." (PMID 26055507, 2015). "Compared to Western blot, QDot multicolor cellular imaging enabled direct and concurrent accesses to intracellular target proteins related to TNF-α-induced insulin resistance." (PMID 25623542, 2015). "Most cross-sectional studies show that circulating TNF-α concentrations are increased in the second and third trimesters, correlate with pre-pregnancy BMI and predict insulin resistance and GDM." (PMID 26110385, 2015). "This property enables multicolor cellular imaging for simultaneous monitoring of many relevant proteins involved in TNF-α-induced insulin resistance." (PMID 25623542, 2015). "Collectively, our data establish that the transcriptional co-activator binding protein, PIMT, mediates TNF-α induced insulin resistance in the skeletal muscle via the transcriptional modulation of several genes associated with glucose uptake." (PMID 26468734, 2015). "LOX is downregulated during adipocyte differentiation, and our data shows that inhibition of LOX impacts adipocyte homeostasis and improves insulin resistance in the well-established model of TNFα-induced insulin resistance." (PMID 26035864, 2015). "Studies reported that administration of TNF-α increased the glucose homeostasis and insulin resistance in animals and humans." (PMID 25789857, 2015). "Hepatic PGC1α has the ability to down-regulate several inflammatory cytokines, including tumor necrosis factor α (TNF-α), and is associated with hepatic insulin resistance." (PMID 26168159, 2015). "The fasting glucose, insulin, insulin resistance, and tumor necrosis factor alpha and erythrocyte enzymatic antioxidants were measured." (PMID 25650289, 2015). "While recent studies suggested that TNF-a enhanced the insulin resistance in infection by inhibiting insulin-induced tyrosine phosphorylation of insulin receptor substrate-1(IRS-1)." (PMID 26137892, 2015). "In a feed forward cycle, the ligand-RAGE signaling results in the up-regulation of RAGE along with the proinflammatory mediators, viz., IL-1β and TNF-α to promote the development of insulin resistance by disturbing insulin signaling." (PMID 25679220, 2015). "Collectively, we conclude that PIMT mediates TNF-α induced insulin resistance at the skeletal muscle via the transcriptional modulation of GLUT4, MEF2A, PGC-1α and HDAC5 genes." (PMID 26468734, 2015).
Insulin resistance (continued). "M1 macrophages secrete various pro-inflammatory cytokines, such as TNF-α and IL-6, which induce insulin resistance via the IKKβ- and JNK-mediated inhibitory serine phosphorylation of insulin receptor substrate (IRS) proteins." (PMID 26197341, 2015). "Additionally, increases in free fatty acids (FFA), interleukin (IL)-6, tumor necrosis factor (TNF)-alpha, together with other pro-inflammatory cytokines that occur with adipose tissue inflammation and changes in adipose tissue function are also associated with insulin resistance." (PMID 26893932, 2015). "TNF-α and IL-6 are produced by adipose tissue monocytes and macrophages and lead to insulin resistance." (PMID 26110385, 2015). "Until now, many studies have been conducted to investigate the mechanism of TNF-α-induced insulin resistance based on Western blot." (PMID 25623542, 2015). "TNF-α is known as a major inflammatory mediator, which induces insulin resistance in adipose tissue." (PMID 25816341, 2015). "Collectively, this leads to the suggestion that there is a connection between insulin resistance and a potential neuroinflammatory response via up-regulation of TNFα." (PMID 26041981, 2015). "It was also shown that anti-TNFα treatment decreases the insulin resistance in type II diabetes mellitus." (PMID 26576191, 2015). "For example, Grimble proposes in a review in 2002 over inflammatory status and insulin resistance that TNF-α, via reduced phosphorylation of a subunit of the insulin receptor, contribute to development of insulin resistance." (PMID 26457080, 2015). "For TNFα, our findings are consistent with previous animal studies showing improved insulin sensitivity following deletion of TNFα or TNFα receptors and human studies demonstrating correlation of TNFα with insulin resistance in the Framingham Offspring study." (PMID 26549941, 2015). "As an anti-inflammatory cytokine, IL-6 was reported to inhibit the effects of proinflammatory TNF-α, promote M2 macrophage polarization, and improve insulin resistance." (PMID 26200663, 2015). "The effect of the test compounds on the suppression of TNF-α-induced insulin resistance was validated through kinase monitoring." (PMID 25623542, 2015). "EPC levels in JIA patients were negatively correlated with index of insulin resistance (rho = -0.458, p = 0.021), endogenous insulin (rho = -0.472, p = 0.017), triglyceride (rho = -0.438, p = 0.029) and TNF-alpha levels (rho = -0.446, p = 0.026)." (PMID 25705139, 2015). "Studies using neutralizing antibodies demonstrated a role for TNFα as mediator between myeloid Fas and skeletal muscle insulin resistance, supported by significant correlations between monocyte Fas expression and circulating TNFα in humans." (PMID 24203314, 2014). "Our data suggest that moderate hyperinsulinemia in response to insulin resistance or lowering of TNF-α levels within the aorta attenuates vascular damage, this protective effect being mediated by UCP-2 expression levels through iNOS." (PMID 25077985, 2014). "This has been shown through in vivo murine studies to involve NF-κB activation and is once again characterised by the production of cytokines, such as IL-6, IL-1, and TNFα, resulting in both hepatic and systemic insulin resistance." (PMID 24830559, 2014). "Inflammatory cytokines, including TNF-α, IL-6, and IL-8, have been involved in the pathogenesis of insulin resistance." (PMID 25202741, 2014). "Disproportionate lipid accretion from excess caloric intake promotes infiltration of innate immune cells followed by increased secretion of cytokines such as IL‐1β and TNFα which instigate a chronic inflammatory response resulting in insulin resistance." (PMID 25096554, 2014). "Release of TNF-α and leptin from placenta during pregnancy is considered to be a diabetogenic factor exacerbating insulin resistance." (PMID 25202741, 2014).